AKT1 (AKT serine/threonine kinase 1)
Diseases named in the same sentence as AKT1 in open-access papers (continued):
Sharing a sentence is not in itself a finding about the gene and the disease.
lung carcinoma (continued). "In both a transgenic and viral-oncogene induced mouse model of lung cancer, Akt1 ablation delayed and decreased tumorigenesis while Akt2 ablation accelerated and promoted tumorigenesis." (PMID 29470540, 2018). "The collective results indicate that RhebL1 is involved in sphingosylphosphorylcholine-induced events in A549 lung cancer cells via binding to AKT1 leading to activation of it." (PMID 28209923, 2017). "Spearman correlation analysis showed that the expression of TCRP1 has a positive correlation with p-PDK1, as well as p-AKT1 in lung cancer and gliomas tissues." (PMID 28436990, 2017). "Akt1 or Akt2 knockout in a viral oncogene-induced mouse model of lung cancer demonstrated that Akt1-ablation inhibited, whereas Akt2-ablation enhanced lung tumour initiation, highlighting their functionally diverse roles." (PMID 28082369, 2017). "The collective findings indicate that RhebL1 is involved in SPC-induced events in A549 lung cancer cells by activation of AKT1." (PMID 28209923, 2017). "In summary, particular NRAS, AKT1 and PTEN gene mutations occur with similar rare (~1%) frequency in CNS metastases of NSCLC as in primary lung cancer tumors." (PMID 28097440, 2017). "More importantly, we found that the expression of TCRP1 has a positive correlation with p-PDK1, as well as p-AKT1 in human lung cancer and glioma tissue samples." (PMID 28436990, 2017). "To this aim we suppressed AKT1 and AKT2 expression in an established lung cancer cell line (NCI-H460) that harbours an activating mutation of PIK3CA (E545K) as reported." (PMID 27880728, 2017). "Silencing of Akt1 protein with the siRNA/CHI-g-PEI complex resulted in significant reductions in lung cancer cell survival, proliferation, and metastasis." (PMID 28290155, 2017). "We further analyzed the expression of TCRP1, p-PDK1 and p-AKT1 in primary lung cancer and glioma tissue samples by immunohistochemistry analysis." (PMID 28436990, 2017). "Lung cancer patients were divided into two subgroups (‘RhebL1-high & AKT1-high’ and ‘RhebL1-low & AKT1-low’) on the basis of their median expression level." (PMID 28209923, 2017). "Using 2 human lung cancer cell lines, we observed that a selective AKT1 inhibitor, A-674563, was a more potent regulator of cell survival than the pan-AKT inhibitor, MK-2206." (PMID 26654940, 2016). "Current study evaluated the genetic variants of PIK3CA, AKT1, and AKT2, all of which are genes in PI3K/AKT pathway, to discover their potential associations with the occurrence of RP in lung cancer patients with radiotherapy." (PMID 26645682, 2016). "We decided to use the highly tumorigenic and metastatic lung cancer cells LNM35 to investigate the impact of specific silencing of the Akt1 and Akt2 isoforms on human lung cancer progression." (PMID 26234648, 2015). "Accordingly, endogenous AKT1-E17K mutant detected in lung cancer cells shows enhanced membrane localization, which results in the activation of downstream signalling." (PMID 26053093, 2015). "Accordingly, endogenous Akt1-E17K mutant detected in lung cancer cells shows enhanced membrane localization and activity." (PMID 26486080, 2015). "We have demonstrated previously that RHOB is downregulated by KRASV12 in lung cancer cell lines increasing invasiveness via AKT1." (PMID 26098773, 2015). "However, the studies reporting PIK3CA and AKT1 mutations in patients affected by lung cancer, and in particular in a subset with squamous cell carcinomas for which no targeted therapy is available yet, have suggested that these genes may represent relevant therapeutic targets for these patients." (PMID 26053093, 2015). "Altogether, these results strongly suggest that both Akt1 and Akt2 plays a role in lung cancer cell invasion and perhaps - by extrapolation - in metastasis." (PMID 26234648, 2015).
lung carcinoma (continued). "Using RNA interference selectively targeting Akt1 and -2 isoform, we explored their respective roles in the human lung cancer cells’ proliferation and colony growth in vitro and in tumor growth in vivo as well as its role in cell motility and invasion." (PMID 26234648, 2015). "Preliminary results indicate IL-24 effectively inhibits Akt1/2 and its downstream target mTOR in lung cancer cells resulting in inhibition of cell growth, cell migration and invasion." (PMID 24377906, 2013). "Many factors including EGFR, HIF-1A, AKT1 and RAF-1 are known to be regulated by Hsp90 and their abnormal expression level is often associated with lung cancers." (PMID 21283735, 2011). "AKT1 is an isoform of AKT that possesses an anti-lung-cancer effect." (PMID 38731403, 2024). "Further, AKT1-induced lung cancer cisplatin resistance is mediated via mTOR-P70S6K1 signaling." (PMID 38200409, 2024). "In non–small cell lung cancer cells, knockdown of AKT1 significantly decreases cell migration." (PMID 36949111, 2023). "As an oncogene, AKT1 expression is upregulated in lung cancer." (PMID 36035842, 2022). "Importantly, AKT1 overexpression and gene amplification were demonstrated to provide cisplatin resistance in lung cancer cells." (PMID 34066040, 2021). "Furthermore, the higher transcription and expression levels of HSP90AA1 and AKT1/ERK pathways were validated in lung cancer patient tissues." (PMID 35095481, 2021). "Akt1 regulates proliferation, survival, and migration in lung cancer-derived DTC." (PMID 32419823, 2020). "However, in lung cancer, Akt1 appears to be more responsible for cell motility, tumorigenesis, and tumor progression similar to thyroid cancer." (PMID 33110146, 2020). "However, in lung cancer, a partial reduction in scratch wound healing migration was observed in Akt2 knockdown cells while the prominent effect was observed in Akt1 knockdown cells." (PMID 31252679, 2019). "To determine the biological significance of FBXW2-mediated β-catenin degradation, we measured effect of FBXW2 on migration and invasion of lung cancer cells, since it was reported that phosphorylation of β-catenin by AKT1 increased its transcriptional activity and promoted cancer cell invasion." (PMID 30918250, 2019). "Therefore, we confirmed that suppression of ERGIC3 decreased Akt1 activation and lung cancer cell proliferation." (PMID 27588471, 2016).
lung carcinoma (continued). "We investigated the impact of specific silencing of Akt1 and Akt2 on human lung cancer cell proliferation, colony growth, motility, and invasion in vitro as well as tumor growth in vivo using human Non-Small Cell Lung Cancer cells LNM35, and on the vascular tube formation using HUVEC cells." (PMID 26234648, 2015). "Akt1 inhibitors may be helpful in malignancies when Akt1 drives survival, such as in lung cancers." (PMID 40483365, 2025). "Human lung cancer cells showing mutated K-ras and reduced AKT1 did not grow in vivo." (PMID 36286049, 2022). "Therapies targeting AKT1 mutated cancers showed that treatment with AZD5363, an ATP-competitive pan-AKT kinase inhibitor, yielded durable responses and tumour regressions across a variety of tumour types harbouring the E17K mutation including breast, endometrial, cervical, and lung cancers." (PMID 35317488, 2022). "Therefore, new bone-targeted agents targeting AKT1, such as DR, will show promise in lung cancer." (PMID 32419823, 2020). "This may account for the finding that AKT1 mutations are detected in a small fraction of lung cancer patients (0.5–2%) and are not selected for in human NSCLC cell lines." (PMID 26859676, 2016). "To verify this hypothesis, we selected seven potentially functional SNPs from three genes in PI3K/AKT signaling pathway, PI3CA, AKT1, and AKT2 to discover their potential associations with the occurrence of severe RP in lung cancer patients treated with radiation therapy." (PMID 26645682, 2016). "Despite the small numbers in these rare lung cancer subtypes, SNV calling using the OncoMap database revealed previously undescribed SNV in FGFR1, CDKN2A, RB1, JAK3, and CTNNB1 for the large-cell type, a BRAF mutation for carcinoid, and an AKT1 mutation for adenosquamous carcinoma." (PMID 26076459, 2015). "Furthermore, Par-4 has been shown to be inactivated by AKT1 in prostate cancer cells, and a Par-4/AKT1 interaction is widely found in prostate cancer, lung cancer, cervical cancer, as well as in benign prostatic hyperplasia and normal human embryonic lung fibroblasts." (PMID 20433755, 2010). "In addition to amplifications in multiple AKT isoforms in pancreatic, ovarian and head and neck cancers, a somatic missense mutation in the PH domain of AKT1 (E17K) was identified in breast, colorectal, ovarian and lung cancers and in melanoma." (PMID 19491896, 2009). "AKT1, EGFR, HSP90AA1, SRC, and STAT3 exhibited the highest degree values and were identified as core therapeutic targets for lung cancer." (PMID 41465428, 2025). "Five core protein targets, AKT1, EGFR, HSP90AA1, SRC, and STAT3, were identified as potential mediators of steamed PJR’s anti-lung cancer effects." (PMID 41465428, 2025). "Five core targets, AKT1, EGFR, HSP90AA1, SRC, and STAT3, were identified as key mediators of its anti-lung cancer action, participating in critical signaling pathways including MAPK, PI3K-Akt, and Ras pathways." (PMID 41465428, 2025). "Collectively, these findings suggest that AKT1, EGFR, HSP90AA1, SRC, and STAT3 represent important therapeutic targets for anti-lung cancer intervention." (PMID 41465428, 2025). "Akt1 and Akt2 were characterized as suppressors for E-cadherin expression in PANC-1 as well as H23 lung carcinoma cells." (PMID 38291468, 2024). "Sequential ablation of AKT1 in tobacco- and K-Ras-treated mice inhibits further lung tumor progression, and the same phenomenon has been observed in IGF-IR positive lung cancer." (PMID 38731403, 2024).
lung carcinoma (continued). "The results showed that the mRNA expressions of AKT1, EGFR and IGF1R were upregulated in lung cancer tissues, while the expression of PI3KR1 was downregulated compared with normal lung tissues." (PMID 37533633, 2023). "In vitro, it was shown that the RHOB/PP2A/AKT1/RAC1 pathway regulates mesenchymal migration and invasion in lung cancer through implication of a PP2A-B55 complex." (PMID 37170215, 2023). "Based on these findings and the results of GO analysis, the mechanism of action of GQZ in the treatment of lung cancer, especially NSCLC, involves the PI3K/AKT1 signaling pathway." (PMID 36591458, 2022). "On the other hand, PRMT5 has been shown to activate the AKT1 and ERK signaling pathways by modifying histone H4R3, thereby promoting metastasis of lung cancer cells." (PMID 35531958, 2022). "It was observed that the mRNA expression of EGFR, MAPK1, Akt1, and SRC were upregulated in the lung cancer tissues whereas the expression of IGF1 and PI3KR1 was reduced as compared to the normal lung tissues." (PMID 36313358, 2022). "In network analysis, the hub targets of cinobufotalin injection against lung cancer were identified as VEGFA, EGFR, CCND1, CASP3, and AKT1." (PMID 32148531, 2020). "SPC-induced RhebL1 binds to Akt1 and activates Akt1, which is involved in keratin phosphorylation and reorganization induced by SPC, promoting the migration and infiltration of lung cancer cell lines." (PMID 31683697, 2019). "Akt1 phosphorylation was also increased in hypoxic A549 cells; HIF-2α expressing lung cancer cells had a higher phospho-Akt1 expression compared to control or HIF-1α expressing cells." (PMID 31817513, 2019). "This study investigated the role of miRNAs as effectors of increasing the AKT1 and AKT2 gene numbers within lung carcinomas." (PMID 30845775, 2019). "The mRNA transcripts of AKT1 and PTEN were upregulated (p < 0.05), while GSK3ß, CCND1 and P21 levels were downregulated (p < 0.05) in Odo A-treated lung cancer cells compared to the control group." (PMID 40141789, 2025). "AKT1, EGFR, and STAT3 were enriched in the non-small cell lung cancer (NSCLC) pathway according to Kyoto Encyclopedia of Genes and Genomes analysis, indicating a significant connection to lung cancer development." (PMID 38731403, 2024). "Western blot analyses revealed that the protein expression of AKT1, IL6, VEGFA, MMP9 in lung tissue of COPD and lung cancer was significantly increased in the model group and hesperetin could dose-dependently prevent these protein expressions (P < 0.01)." (PMID 34262419, 2021). "Indeed, an analysis of data derived from The Cancer Genome Atlas (TCGA) revealed an inverse correlation between the expression levels of oncogenes (HRAS and AKT1) and CFLAR in breast and lung cancer samples." (PMID 34545139, 2021).
lung carcinoma (continued). "In both human and mouse lung cancer cell lines, knocking down HSP90AA1 promoted cell apoptosis through the inhibition of the pro-survival effect of AKT1 by decreasing the phosphorylation of itself and its downstream factors of mTOR and BAD, as well as downregulating Mcl1, Bcl-xl, and Survivin." (PMID 35095481, 2021). "Another study also found that MicroRNAs can inhibit cell proliferation, migration and invasion of lung cancer, regulate cell cycle distribution and epithelial-mesenchymal transition (EMT), the mechanism of which is related to down-regulation of AKT1 expression." (PMID 33250766, 2020). "To identify the genes that are targets of constitutive PI3K/AKT signalling in lung cancer cells, we performed a comparative transcriptomic analysis of human lung epithelial cells (BEAS-2B) expressing active mutant AKT1 (AKT1-E17K), active mutant PIK3CA (PIK3CA-E545K) or that are silenced for PTEN." (PMID 28662101, 2017). "In particular, miR-196a, the DEM that showed the highest average fold change (>2) in all three derivatives of BEAS-cells (AKT1-E17K, BEAS-PIK3CA-E545K and BEAS-shPTEN), emerges as a critical player of PI3K signaling in lung cancer, regulating several oncogenic molecular networks." (PMID 27880728, 2017). "In summary, pre-clinical studies present compelling evidence that targeting AKT1 is an effective strategy to impair lung cancer development and future clinical trials on NSCLC may benefit by incorporating AKT1 inhibitors into their therapeutic strategy." (PMID 26654940, 2016). "We also show that Akt1 has only a minimal role in LNM35 lung cancer cell proliferation and has no impact in colony growth." (PMID 26234648, 2015). "The Prx6 and Trx 1 overexpression had been reported to activate AKT1 or/and EKR1/2 signaling pathways in lung cancer or ischemia, we now showed in reverse that AL-1-activated AKT1 and ERK1/2 could increase the expression of Prx5 and Trx1." (PMID 23750203, 2013). "In AKT1 (r = −0.15, p < 0.05), BRAF (r = −0.25, p < 0.05), GAPDH (r = −0.3, p < 0.05), KRAS (r = −0.24, p < 0.05), MYC (r = −0.25, p < 0.05), and SRC (r = −0.24, p < 0.05), stromal score was negatively correlated with lung cancer and the highest correlation coefficient was in GAPDH." (PMID 39734333, 2024). "Taken together, DDP treatment downregulates the WT1 expression through the PI3K/AKT signaling pathway, and there is a feedback between WT1 and AKT-1; WT1 is involved in cellular proliferation in A549 cells, WT1 inhibition in combination with DDP will provide a new light for lung cancer therapy." (PMID 24228711, 2013).
lung carcinoma (continued). "The potential opposing roles of Akt1 and Akt2 in lung tumorigenesis suggest that development of non-selective Akt inhibitors may not be beneficial and in fact, may be detrimental, particularly in the case of lung cancer in never smokers." (PMID 24722238, 2014). "In the A549 lung cancer cell line (in which EGF receptors are overexpressed), the phosphorylation levels of ERK1/2, STAT3, and AKT1 were not altered by GTN057 when these cell lines were activated by epidermal growth factor (EGF) stimulation." (PMID 36825580, 2023).